CD34 (CD34 molecule)
Diseases named in the same sentence as CD34 in open-access papers (continued):
Sharing a sentence is not in itself a finding about the gene and the disease.
glioma (continued). "In this study, the heterogeneity index α was observed with a significant inverse correlation with anti-CD34 labelled vascularity in all gliomas." (PMID 37182187, 2023). "In gliomas, the CD34-positive cells are recruited by bone-marrow-derived circulating hematopoietic progenitors." (PMID 35562993, 2022). "Although a few of pediatric gliomas share these molecular features with GNT3,5,10, CD34 expression and BRAFV600E mutation, as an adjunct diagnostic marker, are routinely screened in the diagnosis of GNT5–7." (PMID 36307486, 2022). "In particular, the panel included extracellular and intracellular antigens expressed on normal brain and tumor cells (e.g. GFAP, CD140α, CD90), stem cells and glioma cancer stem cells (e.g. Nestin, Musashi-1, CD34)." (PMID 36568177, 2022). "The level of expression glioma-characteristic genes (e.g. CD34, GFAP, OLIG2, MAP2, MKI67, RBFOX3, SOX2, SYN; Suppl." (PMID 34545083, 2021). "After applying the shape filter, we found a linear relationship between the density of putative CD34+ endothelial cells and the density of PpIX+ cells (slope = 0.23 ± 0.05, R2 = 0.74, P = .006, n = 8 IDH1mut gliomas)." (PMID 33959713, 2021). "Specimens from seven glioma cases were analyzed by immunohistochemical staining for CD34, lymphatic endothelial hyaluronic acid receptor 1 (LYVE‐1), prospero‐related homeobox 1 (Prox1), nestin, and hypoxia‐inducible factor 1α (HIF‐1α)." (PMID 31960509, 2020). "So in the current study, we try to use radiomics features to initially identify four markers of Ki-67, vimentin, S-100 and CD34, which are histological markers recommended in several gliomas diagnosis." (PMID 31968004, 2020). "In vivo xenografts of human glioma stem cells were observed to develop tumor vessels with endothelial cells expressing human endothelial proteins CD34, CD144, and VEGFR2." (PMID 31690961, 2020). "The other three markers of vimentin, S-100 and CD34 have been studied rarely for gliomas as a single marker and frequently utilized as co-staining histological markers for differential diagnosis or prognostic prediction." (PMID 31968004, 2020). "This study shows that CD34, VWF, and AQPs are associated with post-IR GSCs glioma relapse and provides essential insights for the development of treatment regimens for radioresistant tumors." (PMID 31803626, 2019). "To validate the correlation between VM and pathological grade of glioma, we conducted the CD34-PAS dual-staining." (PMID 30744670, 2019). "CD34 expression has been demonstrated to play a crucial role in the regulation of glioma angiogenesis by promoting a new blood vessel network and driving further glioma growth." (PMID 29884885, 2018). "The implications and utilities of CD34 in WHO grades of gliomas and its prognosis have been reported rarely." (PMID 26886640, 2016). "In our study, we extracted data from published articles and systematically assessed CD34 regarding gliomas’ WHO grades and prognosis." (PMID 26886640, 2016). "The exact role of CD34 in grading and determining a prognosis for gliomas, however, is still unclear and under debate." (PMID 26886640, 2016). "As shown by molecular stains, such as CD34, there is an increase in the number of tortuous vessels, giving rise to a ‘‘swamp” of numerous, small slow-flowing vessels in gliomas." (PMID 27584684, 2016). "We carefully assess the relevant articles and standard mean differences (SMDs) with 95% confidence intervals (95% CIs) were estimated in terms of the relationship between CD34 expression levels with gliomas’ WHO grades, patients’ ages and gender." (PMID 26886640, 2016). "We found that the levels of HULC, VEGF, ESM-1 (endothelial cell specific molecule 1) and microvessel density (MVD) (CD34) were correlated in glioma patient tissues of various grades." (PMID 26894862, 2016).
glioma (continued). "Neuropathological assessments revealed tissue areas at the resection margins corresponding to TZ II, and postoperative CD34- and Map2 immunostaining confirmed these angiogenic hotspots to be occupied by glioma cells." (PMID 25609379, 2015). "A C6 glioma cell line, a culture of hematopoietic CD34+/CD133+ stem cells and primary cultures of rat astrocytes and fibroblasts were used." (PMID 25789053, 2015). "It was revealed that the amount of α-SMA positive cells, the pericytes, was even higher than that of CD34-positive ECs in high grade glioma." (PMID 25478951, 2014). "Microvessels in gliomas, specifically stained by anti-CD34 immunostaining, were observed in all specimens, and scored as IMD." (PMID 23688241, 2013). "Blood vessels were often abnormal with signs of endothelial hyperplasia and microvascular proliferation with prominent CD34 staining, reminiscent of typical high grade glioma pathology." (PMID 24252742, 2013). "CD34 has been shown to be closely related to angiogenesis, which is a key determinant in the progression of glioma." (PMID 22729482, 2012). "Research has shown that CD34 is significantly overexpressed in high-grade gliomas." (PMID 40892951, 2025). "Therefore, there is an urgent need to develop an automated analysis method that offers good interpretability, integrates glioma-specific pathological prior knowledge, and robustly handles the complexities of CD34-stained images." (PMID 40892951, 2025). "Ganglioglioma may also be included in the differential diagnosis of F3T3 gliomas, as it shares characteristics such as desmoplasia, CD34 extra-vascular immunostaining, and microcalcifications." (PMID 38730596, 2024). "SEM-derived DDC and α are significant in histologically grading gliomas, DDC may indicate the proliferative ability, and CD34 stained microvascular perfusion may be an important determinant of water diffusion inhomogeneity α in glioma." (PMID 37182187, 2023). "Moreover, CD34-PAS immunohistochemical staining showed that glioma cell VM density was significantly increased under HOTAIRM1 overexpression and prominently reduced under HOTAIRM1 depletion." (PMID 38012763, 2023). "Notably, we determined the expression of CD31 and CD34 in human glioma specimens (n = 85, N095Ct01, Bioaitech)." (PMID 36708044, 2023). "The results indicated that L1 expression is positively correlated with CD31/CD34 expression in glioma, suggesting that L1 overexpression could affect VM formation in glioma." (PMID 36708044, 2023). "Further immunohistochemical staining showed that after reducing the HOTAIR expression of gliomas, the expression of PPARΑ protein was increased, and the CD34 and Ki67 protein expression of the combined treatment group was lower than that of the other two groups." (PMID 34082742, 2021). "Similarly, CD34+-ECs cultured with pericyte-glioma (DIPG-007, DIPG-013 and DIPG-014) BBTB were more permeable than EC–pericyte–astrocyte BBBs." (PMID 33668807, 2021). "CD34 is popular as a vessel marker and is demonstrated to regulate the glioma angiogenesis and could help gliomas grading." (PMID 31968004, 2020). "The precise identification of CD34 noninvasively could help predicting angiogenesis-related gliomas progression." (PMID 31968004, 2020). "Additionally, many vessels formed by LYVE‐1+/CD34+ cells were seen in the gliomas, along with many red blood cells." (PMID 31960509, 2020). "Next, to assess if key T cell subsets independently predict glioma progression, Cox multivariate regression analyses were performed (by including factors, such as age, sex, chemo/radiotherapy, CD34+ circles and perivascular/intratumoral infiltrating T cell subsets)." (PMID 29163521, 2017). "CD34 is widely distributed in the tumor vascular endothelial cells in gliomas." (PMID 27069921, 2016). "Different levels of CD34 staining were localized in glioma vascular endothelial cells." (PMID 26872471, 2016).
glioma (continued). "In grade II glioma, most of tumor MVs were the thin-wall CD34+ vessels with near normal morphology." (PMID 25478951, 2014). "CD34 was mainly expressed in the cytoplasm or membrane of vascular endothelial cells and was often tubular, streak-like, comma-like and lumpy in staining shape, and it was much greater in high-grade gliomas than in low-grade tumors." (PMID 24348828, 2014). "Our study indicates that SEM-derived parameters DDC and α are significant in histological grading of gliomas, DDC may indicate proliferative ability, and CD34-stained microvascular perfusion may be an important determinant of water diffusion inhomogeneity α in gliomas." (PMID 37182187, 2023). "In addition, CD34 might have strong potential in predicting gliomas survival and therapy effectiveness." (PMID 31968004, 2020). "Rahmah et al11 found that high-grade gliomas showed higher expression of CD34, which suggested that high-grade glioma may have higher densities of vessel, whereas Netto et al13 found high expression levels of CD34 in the endothelial cells in their oligodendroglioma study." (PMID 26886640, 2016). "This means that CD34 could be a potentially prognostic factor of gliomas." (PMID 26886640, 2016). "In glioma tissue sections, it was observed that the expression levels of IDO1, VEGFA, and CD34 were positively correlated with the pathological grades, with expression levels in grade III/IV glioma patients significantly higher than in patients of lower grade." (PMID 39065567, 2024). "It has also revealed that TLR-4 activation (1 μg/ml) stimulates the secretion of the inflammatory cytokines (TNFα and ILs) and up-regulation of specific stem cell markers, including CD34 and CD133 in human glioma U251 cells." (PMID 38698968, 2024). "Some well-known ancillary markers of grading gliomas, such as anti-MIB-1/Ki-67 and anti-CD34, are closely related to tumor cell proliferation and microvascular density." (PMID 37182187, 2023). "We postulated that immunohistochemical detection of proteins expressed preferentially in gliomas (EGFR, MEOX2, CD34) or during embryonal development (SOX11, INSM1) can be used to distinguish reactive gliosis from glioma." (PMID 37568909, 2023). "Three types of vessels were observed in glioma specimens: LYVE‐1+ lymphatic vessels, CD34+ blood vessels, and LYVE‐1+/CD34+ blood vessels." (PMID 31960509, 2020). "We identified the VMs and endothelium-dependent vessels in the gliomas by double staining for PAS and CD34." (PMID 29113309, 2017). "After calculating the correlations among the expression levels of HULC, VEGF, ESM-1 and MVD (CD34), we observed a significant linear correlation between HULC, VEGF, ESM-1 and MVD (CD34) in primary glioma patient pathological tissue." (PMID 26894862, 2016). "Human glioma stem/progenitor cells can transdifferentiate into vascular endothelial cells (VECs) and express VECs markers including CD31, CD34, and vWF significantly under hypoxia." (PMID 27346985, 2016). "Relative tumor vascular areas (CD31+, CD34+ and IB4+ blood vessels) were significantly increased in Sr-a1−/− gliomas compared with Sr-a1+/+ gliomas." (PMID 27367025, 2016). "We studied the levels of HULC, ESM-1 and angiogenesis (CD34 and VEGF) in the tissues of glioma patients." (PMID 26894862, 2016). "Therefore, it is unclear whether CD34 can be used as a marker of WHO grades in gliomas." (PMID 26886640, 2016). "In this study we adopted immunohistochemistry assay to detect CD34, MMP-2, and other indicators in glioma tissue." (PMID 26788112, 2015). "Diffuse gliomas with FGFR3::TACC3 fusion display unique histopathological and molecular features, including an oligodendroglioma-like appearance, calcifications, and CD34 extravascular immunoreactivity." (PMID 38730596, 2024).
glioma (continued). "Besides, the clinical glioma specimen's immunohistochemistry results also demonstrated a positive correlation between SPRY4‐IT1 value and vascular endothelial marker (CD34)." (PMID 36479622, 2023). "Meanwhile, GA-MSCs lack expression of CD133 or CD34, which suggests they are not glioma stem cells or endothelial cells." (PMID 37005685, 2023). "Additionally, we found that L1 overexpression resulted in upregulation of several VM formation‐related factors, including CD31, CD34, VEGFA, vimentin, and N‐cadherin, whereas it downregulated E‐cadherin expression in glioma cells." (PMID 36708044, 2023). "In this study, SEM-derived intravoxel water diffusion heterogeneity α had a moderately to good negative correlation with CD34 expression rate in glioma by MDWI using a narrow-low range of multi-b-value combination." (PMID 37182187, 2023). "There was a moderate to good negative correlation for all gliomas between CD34-MVD with α1500 (r =-0.437; P =0.012)." (PMID 37182187, 2023). "Moreover, the number of CD34+α-SMA− veins in the tumor area was less than in the contralateral area, which indicated that the para-venous efflux of ISF was lower in the glioma." (PMID 35083148, 2021). "We then showed VM structures in glioma tissue by double staining for PAS and CD34." (PMID 33535172, 2021). "Furthermore, double staining for PAS and CD34 showed that miR-29a-3p overexpression and EXO-29a treatment hampered the VM formation abilities in xenograft gliomas." (PMID 33535172, 2021). "Trans-differentiation of glioma cells to endothelial cells in vitro was demonstrated by culturing of glioma cancer stem cells in endothelial-promoting media, resulting in expression of pan-endothelial markers CD31, CD34 and vWF, formation of tubular structures and uptake of LDL." (PMID 31690961, 2020). "NES, CD34 nor PECAM1 expression was associated with prognosis in urothelial cancer, lung cancer, stomach cancer or glioma." (PMID 30279450, 2018). "Only one of the many studies that have examined CD34 expression in gliomas found tumoral (as opposed to endothelial) immunoreactivity in lesions classified as WHO grade II or III astrocytomas, oligodendrogliomas or oligoastrocytomas." (PMID 27812792, 2017). "Antiangiogenesis effect was also evaluated in the rat model of orthotopic glioma allograft, based upon markers including relative cerebral blood volume (rCBV) by magnetic resonance imaging (MRI), VEGF levels and microvessel density (MVD)/CD34 staining." (PMID 26872471, 2016). "Of these, 81 were excluded on the basis of the title and abstract: 29 had no relevance with gliomas, 36 had no relevance for CD34 studies, and 16 were in vivo or in vitro studies." (PMID 26886640, 2016). "Furthermore, there was a positive correlation between the level of HULC, ESM-1, MVD (CD34) and VEGF in glioma patient tissue, suggesting that there was a potential relationship between HULC, ESM-1 and angiogenesis in the tumor progression." (PMID 26894862, 2016). "It should be mentioned that the CD34+-MVND was not correspondingly increased in WHO grade IV glioma when compared with that in grade III, while the α-SMA+ MV area was obviously enhanced in this research." (PMID 25478951, 2014). "The α-SMA+MVND/CD34+ MVND ratio increased from 35.57% in grade II to 76.36% in grade IV, suggesting the preferential proliferation of pericytes and more pericyte-contained MVs in high grade glioma." (PMID 25478951, 2014). "In addition to thin-wall CD34+ MVs, more thick-wall MVs were found in grade III glioma, which often showed α-SMA positive." (PMID 25478951, 2014). "Immunofluorescence staining showed that cells, expressed simultaneously CD34,CD133,KDR and Hoechst 33342, appeared in the tumors, which proved that EPCs derived from donors incorporated into the tumors and contributed to the growth of glioma." (PMID 22720671, 2012). "The lumina‐lining cells of capillaries in glioma were invariably positive for CD31, CD34 and CD105." (PMID 19067716, 2010).
glioma (continued). "Moreover, the transcription of CD34, EMCN (another marker of endothelial tumor cells) and CD248 was increased in the GBMwt_hi group compared to the rest of gliomas." (PMID 33147752, 2020). "However, follow-up clinical studies could not confirm the widespread EGFR amplified CD34+ endothelial cells in gliomas, and hence transdifferentiation, while important, may be a rare event in the evolution of gliomas." (PMID 28740831, 2017). "In this connection, we would point out that the “pediatric oligodendrogliomas” (and other low-grade gliomas of the young) reported to date as displaying BRAF and FGFR abnormalities seem not to have been systematically studied for CD34 expression." (PMID 27812792, 2017). "With the increase of glioma grades, the α-SMA+ MVND, CD34+ MVND and MPND were significantly augmented although the increase of CD34+ MVND but not MPAD was statistically insignificant between grade III and IV." (PMID 25478951, 2014). "In all distinguished types of glioma blood vessels, the lumina‐lining endothelial cells were positive for CD31 and CD34, while none of the other cellular components were positive for these markers." (PMID 19067716, 2010). "Additionally, the expression of the negative MSC markers CD11b, CD34 and CD45 did not correlate significantly with the prognosis of glioma patients." (PMID 32452829, 2020).